FAP (fibroblast activation protein alpha)
Diseases named in the same sentence as FAP in open-access papers (continued):
Sharing a sentence is not in itself a finding about the gene and the disease.
tumor (continued). "To mimic fibroblast transformation in the tumor microenvironment, we co-cultured TNBC cells and fibroblasts for 2 days and then examined the mRNA and protein levels of the CAF markers FAP and α-SMA." (PMID 34692516, 2021). "U87 cells, either alone or mixed with FAP+ mesenchymal cell cultures or with HBVP, were xenografted on a chorioallantoic membrane and allowed to form tumours." (PMID 34282761, 2021). "Approximately 2% of TASCs isolated from EO771 tumours expressed syndecan‐2, 1.94 ± 0.35% syndecan‐2+FAP− and 0.02 ± 0.008% syndecan‐2+FAP+ (mean ± SEM, n = 3 tumours from 3 different mice)." (PMID 33152121, 2021). "FAP inhibitors (FAPI) were therefore developed as anti-cancer drugs and then as tumor-targeting radiotracers." (PMID 34203923, 2021). "FAP-specific CAR T cells function to deplete most FAP + cells and restrict tumor stroma generation, along with promoting the uptake and antitumor effects of chemotherapeutic drugs, such as gemcitabine." (PMID 34635121, 2021). "In this study, we have shown that high FAP and SPARC expression in tumor stroma and high PDGFRB expression in tumor cells are associated with shorter survival in MPM patients in univariate analysis." (PMID 33955203, 2021). "To investigate the expression of LOX in tumor stroma, we also evaluated the expression of LOX and CAFs markers α-SMA and FAP in OSCC clinical samples by multiplex IHC staining." (PMID 34930321, 2021). "We confirmed the impact of the CAF-S1 content on distant recurrence by using FAP histological scoring, as a specific marker of CAF-S1 quantity per tumor." (PMID 32665033, 2020). "We found that tumor-secreted exosomes strongly induced α-SMA and FAP expression compared with Het-1a cell-secreted exosomes." (PMID 32637576, 2020). "This analysis aims to introduce a novel approach of tumour detection, contouring and targeted radiotherapy of HNCs using visualisation of CAFs: PET-CT with 68Ga-radiolabeled inhibitors of FAP (FAPI)." (PMID 32447444, 2020). "Fibroblasts were first activated using CM secreted by tumour cells, and their activation was confirmed by expression increase of PDGFR‐α, FAP‐α and α‐SMA (Fig EV3E) markers." (PMID 33025708, 2020). "Targeting the stromal cells by the FAP-specific CAR T-cells will allow and lead to infiltration of the tumor by TILs." (PMID 32582537, 2020). "Thus, FAP expression may be a common feature of tumor pericytes." (PMID 33082953, 2020). "We present data that support that the fibroblast activation protein-α (FAP), a CAF biomarker, provides interesting information both in tumour tissues and in plasma from patients with RCC." (PMID 33207686, 2020). "For instance, in the case of RO7386, a 2:2 BsAb targeting FAP and DR5 using high-affinity bivalent FAP arms ensured tumor-selective targeting, whereas bivalent low-affinity DR5 arms facilitated DR5 hyperclustering and killing of tumor cells." (PMID 32989604, 2020). "FAP is another wide-spread biomarker for CAFs, as well as a serine protease participating in ECM remodeling and fibrogenesis, thereby accelerating tumor progression." (PMID 33292666, 2020). "When interacting with CAFs, nanoparticles disassembled rapidly under FAP-α's cleavage and efficiently released DOX specifically at the tumor sites." (PMID 32775317, 2020). "Several tumor-antigen targets, such as MSLN, WT-1, FAP and the antigens of the ErbB family are evaluated for their applicability for CAR T-cell therapy in MPM." (PMID 32582537, 2020). "The reactive CAF population that we determined to be a dominant factor in inducing FSS resistance in tumor cells expresses higher ?-SMA and FAP compared to differentiated CAF." (PMID 32256977, 2020). "Hence, fluorescence quenched and activatable HER2’scFv and FAP’scFv bearing bispecific Bi-FAP/HER2-IL could be exploited for tumor imaging purposes for other targeted quenched liposomes, and also for elucidating the features of the HER2’scFv as ligand for nano-therapeutics." (PMID 33076292, 2020).
tumor (continued). "In a transgenic mouse model for pancreatic ductal adenocarcinoma (PDAC), where FAP expressing cells were depleted by injecting diphtheria toxin, CAF depletion led to reduced tumor growth, which was mediated by enhanced CD4+/CD8+ T cell activity." (PMID 32899119, 2020). "An anti-human directed FAP CAR with the CD3ζ and CD28 signaling domains was produced at the University of Zurich and shown to induce killing of tumor cells expressing human FAP." (PMID 32914147, 2020). "While such a model may recapitulate various aspects of disease more accurately than the subcutaneous tumor model used here, we chose the latter since it allowed us to study FAP targeting without the experimental complexity associated with intracranial tumor implantation." (PMID 32806623, 2020). "We show that both monospecific (HER2-IL) and bispecific (Bi-FAP/HER2-IL) formulations are quenched and undergo HER2-dependent rapid uptake and cargo release in cultured target cells and tumor models in mice." (PMID 33076292, 2020). "We identified six TAA protHLAIp that were exclusively detected in the tumor tissue of C3N-02289 (BIRC5, TERT, FAP, SPAG4, MAGEA9, and BCL2L1)." (PMID 32157095, 2020). "Thus, a Bi-FAP/mEnd-IL formulation tailored for the targeting of human endoglin and FAP will be suitable for the targeted delivery of drugs and contrast agents into human neoplastic cells, and the tumor microenvironment components including the TAFs, tumor vasculature and also TAMs." (PMID 32316521, 2020). "HGFs incubated with the OSCC-derived MVs internalized these tumour MVs (TMVs) and subsequently increased levels of CAF markers (FAP and Tn-c)." (PMID 32054041, 2020). "In line with this, infection with the earlier introduced VVs encoding antibodies that target VEGF and EGFR (GLV-1h44), or VEGF and FAP (GLV-1h446) diminished angiogenesis and tumor cell proliferation in human prostate tumor xenografts." (PMID 33167307, 2020). "Inhibition of FAP using an anti-tumor vaccine, monoclonal antibody, or chimeric antigen receptor (CAR) T-cell therapy, affects tumor cell growth and increases the CD8+ T cell response 207-209." (PMID 32754274, 2020). "A study showed that the anti-FAP CAR-T and DNA vaccine inhibits tumor growth in a mouse model of GI cancer." (PMID 31540435, 2019). "FAP-specific binding in vivo was verified for FAPI-21 and -46 by competition experiments, demonstrating a complete block of tumor accumulation by unlabeled compound." (PMID 30850501, 2019). "Finally, α-SMA+FAP+ CAFs were reported to respond to hypoxia and castration-caused tissue damage by promoting CX-chemokine ligand 13 (CXCL13) production, which aided B cells and other immunosuppressive cell trafficking to the TME that establish tumor progression." (PMID 31462327, 2019). "Stromal DKK3 expression in human tumours positively correlated with the expression of CAF markers ACTA2, FAP and COL1A2, supporting a link between DKK3 and CAFs." (PMID 30631061, 2019). "Administration of FAP-CAR T cells into tumor-bearing mice significantly reduced tumor growth and induced apoptosis of tumor cells." (PMID 30987642, 2019). "Along this line, an oral DNA vaccine targeting FAP, a CAF-specific marker, has been demonstrated to suppress tumor growth and metastasis and confer a survival benefit in murine models of CRC and breast cancer." (PMID 31417869, 2019). "For example, anti-FAP CAR T cells can deplete FAP+ cells in PDAC and decrease tumor growth through promotion of antitumor immunity." (PMID 31885581, 2019). "And the remodeling of tumor interstitial microenvironment was shown by the expression of TGFβ1, epidermal growth factor (EGF), fibroblast activation protein alpha (FAPa), matrix metalloprotein 9 (MMP9)." (PMID 31528217, 2019). "α-SMA/neoplastic epithelial area ratio, FAP and SDF-1 were used as indicators for CAFs within the tumor." (PMID 31101063, 2019).
tumor (continued). "In this study, we found that FAP-a is specifically expressed in the stromal fibroblasts of IDC and the tumor-host interface of the invasive front of DCIS-MI." (PMID 31921678, 2019). "Although high FAP-a expression was detected in stromal fibroblasts of IDC and tumor-host interface at the invasive front of DCIS-MI, its correlation with the chemo- or radio-therapy treatment has not been studied because of the limited sample size." (PMID 31921678, 2019). "Once they reached the tumor stroma, CAP-NP rapidly disassembled upon cleavage by FAPα and released the drug." (PMID 30871158, 2019). "In a murine model of pancreatic cancer, FAP-CART reduced extracellular matrix proteins and glycosaminoglycans, decreased tumor vascular density and restrained tumor growth." (PMID 31101063, 2019). "A number of potential targeting strategies exist to block CAF-mediated tumour support, including inhibition of CAF cell-surface proteins (such as the anti-FAP antibody Sibrotuzumab169), blocking CAF activation or by targeting CAF-tumour signalling." (PMID 31308358, 2019). "FAP is involved in ECM remodeling with collagen being a key substrate, herewith facilitating tumor migration." (PMID 30922247, 2019). "Depleting FAP+ CAFs in mice with melanoma also reduced the activity of immunosuppressive cells and improved antitumor activity of CD8+ tumor-infiltrating T cells." (PMID 29686035, 2018). "In a separate study using KPC mice, depletion of FAP+ stromal cells was synergistic with anti‐CTLA‐4 or anti‐PD‐L1 therapy, further demonstrating the role of stroma in suppressing anti‐tumor immunity." (PMID 30003190, 2018). "In this study, we confirmed that FAPα was overexpressed in human ESCC tissues; This result detected in tumor tissues was contrary to the result detected in the plasma of ESCC patients." (PMID 28415791, 2017). "FAP-α, collagen XIA, P4H and PDGFR-β positive cells were highly abundant within the BCC tumour islands and in the near tumour periphery." (PMID 28987144, 2017). "An anti-human directed FAP CAR with the CD3ζ and CD28 signaling domains was produced at the University of Zurich and shown to induce the killing of tumor cells expressing human FAP." (PMID 28862644, 2017). "To create a similar tumor microenvironment, we added tumor cells cultured medium (TCCM) from MM cells to BMSC-cultured medium (1:1), and the expression of FAPα was evaluated again." (PMID 28881756, 2017). "Tumor cells (identified by CEA+ staining) form an external peripheral layer, which surrounds the central core of fibroblasts (identified by FAP+ staining)." (PMID 27858101, 2017). "Treatment of heterotypic spheroids co-cultured with immune cells added to supernatants with CEA TCB or FAP TCB resulted in target-specific cross-linking and retention of T cells to tumor cells or fibroblast areas, respectively." (PMID 27858101, 2017). "In this context fibroblast activation protein alpha (FAP-α) and dipeptidyl peptidase IV (DPPIV) are proteases located at the plasma membrane promoting cell invasiveness, tumor growth, and keloid scar formation." (PMID 29072623, 2017). "Furthermore, FAP+ stromal cells maintain the deposition of extracellular matrix and glycosaminoglycan and promote angiogenesis in the tumour microenvironment such that their ablation improves intratumoural uptake of chemotherapeutic drugs and suppresses tumour growth." (PMID 28158223, 2017). "Treatment with tumor- or fibroblast-targeted TCB antibodies (CEA TCB and FAP TCB, respectively) led to efficient target-specific cross-linking and retention of T cells to tumor cells or fibroblasts, respectively." (PMID 27858101, 2017). "One possibility is that FAP participates in modifying ECM molecules to create and regulate cell adhesion in the tumor microenvironment." (PMID 26934296, 2016).
tumor (continued). "Other selected targets in clinical trials for CAR T cell therapy, an approach that also requires highly tumor-specific targets, include ERBB2, mucin-16 (MUC16), prominin 1 (PROM1) and the prolyl endopeptidase FAP (FAP)." (PMID 26700623, 2016). "This review highlights the role of FAP α in tumor development, explores the relationship between FAP α and immune suppression in the TME, and discusses FAP α as a potential immunotherapeutic target." (PMID 26985769, 2016). "FAP has been reported to cleave type I collagen, which is the most abundant ECM protein in a tumor stroma." (PMID 26934296, 2016). "In particular, cancer-derived soluble factors recruit BM- and AT-derived MSCs to tumor sites, where the latter cells acquire the expression of CAF-specific markers such as α-SMA, FAP, tenascin-C and TSP-1." (PMID 25474039, 2015). "Therefore, the function of FAPα may vary between tumor contexts and require further study." (PMID 25593080, 2015). "Thus, the association between FAP overexpression and other tumor types was not evident." (PMID 25775399, 2015). "Overexpression of FAP in fibroblasts modifies the ECM to form a permissive microenvironment, promoting tumor invasion in human pancreatic cancers." (PMID 24551161, 2014). "The expression of these proteins correlated with tumor areas in which cells had more “active” appearing nuclear features, and high expression of ADAM12, FAP, and WISP1, and low expression of SOX11, correlated with worse clinical outcome." (PMID 24402778, 2014). "The forced expression of FAP in epithelial cells promoted cellular invasion through the extracellular matrix (ECM) and supported tumor growth in various xenograft animal models examined." (PMID 24551161, 2014). "FAP and DPP-IV are known to form a hetero-oligomer in a proteolytic complex, which is involved in the invasion of tumor cells in collagenous matrices." (PMID 24520291, 2014). "Whole tumor sections from representative paraffin-embedded tissue blocks were used to assess the topographic expression patterns of CCN2, EMA, K19, and FAP in scirrhous HCCs." (PMID 25126747, 2014). "Thus, although FAP may be a sufficient target in some murine tumor models, we demonstrate that extracellular enzyme inhibition is insufficient in our models, suggesting intracellular proteases may also be relevant targets for boronated dipeptides with antitumor activity." (PMID 23554941, 2013). "In this work, we quantified the α-SMA+, NG2+, FAP+, FSP+, CD31+, and F4/80+ stromal contributions to the tumor microenvironment." (PMID 22363446, 2012). "Targeting FAP-expressing stromal cells has been shown to inhibit CT26 tumor cell proliferation indirectly, decrease tumour myofibroblast content and blood vessel density." (PMID 24212801, 2011). "This phenotype can be reversed by inhibition of FAP enzymatic activity during matrix production resulting in the disorganization of the ECM and impeded tumor invasion." (PMID 21668992, 2011). "Our FAP+inhibitor matrices resembled FAP- matrices with lower ECM levels of organization and supported relatively impeded tumor cell behaviors." (PMID 21668992, 2011). "In the tumor-host interface of DCIS-MI, stromal fibroblasts exhibited SMA-CD34+FAP-α-, however, in the tumor-host interface at the invasive front of DCIS-MI lesions, stromal fibroblasts exhibited mainly immunophenotype of SMA+CD34-FAP-α+." (PMID 22067528, 2011). "Under both conditions the expression of ADAM23, FAP, GPNMB and PRSS3 genes was much higher in EC isolated from tumor specimens, as shown by the fold difference values." (PMID 18447899, 2008). "In normal-appearing epithelial cells in FAP, PSG9 was expressed mostly on the apical surface, while in tumours, expression was detected from the top to the base of crypts." (PMID 15982419, 2005). "Functionalizing HFn with FAP antibody fragments can significantly enhance the CAF-specific delivery of the drug and compete with the TfR1 receptor, thereby decreasing off-target distribution in tumor cells." (PMID 41328341, 2026).
tumor (continued). "Notably, targeting CAFs, such as through FAP, has been proposed to enhance immunotherapy efficacy; however, developing separate CAR-T cells, one against CAFs and the other against tumor cells, can be complex and costly." (PMID 41596556, 2026). "In contrast, the longer half‐life of 225Ac still does not match the tumor retention profile of second‐generation FAP‐targeting agents, limiting its effect dose delivery." (PMID 40888104, 2026). "In contrast, in normal tissue, there were few SPP1+ macrophages surrounding FAP+ fibroblasts, indicating that the interactivity between them primarily occurs within tumor tissues rather than in normal tissues." (PMID 40438108, 2025). "Second, they suggest that selectively targeting these pathways at their stromal source—using antibodies, small-molecule inhibitors, or fibroblast activation protein (FAP)-guided nanosystems—can normalize CAF function and remodel the tumor microenvironment (TME)." (PMID 41514658, 2025). "Second, although there was a significant negative association between TLSs and CAFs, we did not determine the mechanism by which FAP+ CAFs suppress TLS formation or the role of TLSs in tumor suppression via humoral-immunity-related mechanisms." (PMID 41154405, 2025). "One consideration is the presence of activated fibroblasts within the tumor stroma, rather than the malignant cells themselves, except in some rare tumoral entities with direct FAP expression by the malignant cells." (PMID 41463267, 2025). "The therapeutic use of FAP-targeted radiopharmaceuticals is, however, still in its early stage, mainly due to the lack of tumor retention and resultant low dose delivery." (PMID 41466165, 2025). "Studies have shown that the elimination of FAP+ cells can effectively alleviate the immunosuppressive state within the TME, enhance the function of CD8+ T cells, and thereby prolong the survival of tumor-bearing mice." (PMID 40890855, 2025). "Experimental evidence has demonstrated that FAPα, when its catalytic activity is compromised, can exert both anti-proliferative and pro-proliferative effects on tumor cells, independent of its catalytic function." (PMID 40918451, 2025). "To determine whether 015s similarly alleviates tumour fibrosis in vivo, we evaluated α-SMA, FAP, and COL1A1 expression in EMT-6 tumours by Western blotting." (PMID 40806691, 2025). "To determine whether cCAF levels correlate with corresponding tumor tissue expression, we assessed the expression levels of the CAF markers FAPα as well as αSMA using IHC." (PMID 39815324, 2025). "The antitumor effects of antibody–drug conjugates targeting FAP have been observed and a phase I study of AVA6000, a peptide drug conjugate that releases doxorubicin in the tumor microenvironment of FAP-positive solid tumors, showed antitumor effects while reducing systemic exposure to doxorubicin." (PMID 40126602, 2025). "Various strategies targeting FAP, including small molecule inhibitors, monoclonal antibodies (mAbs), antibody–drug conjugates (ADCs), and chimeric antigen receptor T (CAR-T) cells, have demonstrated therapeutic effects in murine tumor models." (PMID 41228205, 2025). "Sibrotuzumab, a humanized monoclonal anti-FAP antibody, enhanced cytotoxic activity against FAP-expressing tumor cells in in vitro experiments, but had no therapeutic effect observed in clinical studies." (PMID 40607439, 2025). "FAP expression in the primary tumor, however, did not maintain statistical significance as an independent predictor." (PMID 41303595, 2025). "One example of this is the FAPα-activated prodrug Z-GP-DAVLBH, that selectively destroys pericyte-rich vessels, eradicating the otherwise VDAs-resistant tumor rim and leading to complete tumor regression in pre-clinical models." (PMID 41155375, 2025). "In targeting FAP for RLT, tumor cells are influenced through “cross effects”." (PMID 40438601, 2025).